KLF4 (KLF transcription factor 4)
Diseases named in the same sentence as KLF4 in open-access papers (continued):
Sharing a sentence is not in itself a finding about the gene and the disease.
head and neck squamous cell carcinoma (16 papers, 2015 to 2025). A squamous cell carcinoma that arises from any of the following anatomic sites: lip and oral cavity, nasal cavity, paranasal sinuses, pharynx, larynx, and salivary glands. "The association of KLF4 with super-enhancers in head and neck squamous cell carcinomas HNSCC is a further evidence of the architectural role that this TF plays in cancer development." (PMID 39135777, 2024). "In head and neck squamous cell carcinoma, persistent KLF4 expression is associated with a poor disease-specific survival." (PMID 31427673, 2019). "Moreover, an increase in KLF4 expression has been reported in human head and neck squamous cell carcinoma, and its persistent expression was associated with poor prognosis." (PMID 41463190, 2025). "The overexpression of KLF4 has been implicated in the transformation of epithelium in the early development of head and neck squamous cell carcinoma (HNSCC)." (PMID 40552304, 2025). "In contrast, in head and neck squamous cell carcinoma (HNSCC), KLF4 exhibits oncogenic functions through interactions with super-enhancers or other chromatin activation mechanisms." (PMID 39995670, 2025). "Gene expression of KLF4 positive correlated with E-cadherin in 71 head and neck squamous cell carcinoma (HNSCC) patient tissue samples, which we also confirmed by the investigation of the Cancer Genome Atlas database (TCGA)." (PMID 35219646, 2022). "Additionally, in head and neck squamous cell carcinoma (HNSCC), ZSCAN4 played an important role in facilitating chromatin remodeling and activating cancer stem cell factor expression, including OCT3/4, NANOG, KLF4, and SOX2." (PMID 36841776, 2023).
lung adenocarcinoma (16 papers, 2016 to 2025). A carcinoma that arises from the lung and is characterized by the presence of malignant glandular epithelial cells. "KLF4 has emerged in a recent analysis of lung adenocarcinoma (including 497 tumors and 54 adjacent normal tissue samples) as a possible marker." (PMID 41463190, 2025). "This study aimed to evaluate the prognostic significance of epithelial zinc finger protein (EZF/KLF4) in lung adenocarcinoma (LAC) and explore its potential roles in tumor progression and immune regulation." (PMID 40533866, 2025). "According to the GEPIA database, KLF4 expression was significantly reduced in lung adenocarcinoma (LUAD) and lung squamous carcinoma (LUSC)." (PMID 38808570, 2024). "Loss of USP10 downregulates KLF4 expression and accelerates KRASG12D-driven initiation and progression of lung adenocarcinoma." (PMID 36969062, 2023). "We transduced OCT3/4, SOX2, and KLF4 (hereafter, OSK) or EGFP into a KRAS-mutated (G12S) human lung adenocarcinoma cell line (A549) using retrovirus vectors, then cultured the cells in 10% fetal bovine serum (FBS) containing Dulbecco’s modified Eagle’s medium (DMEM)." (PMID 28951614, 2017). "Spheres derived from the lung adenocarcinoma cell line, H1299, exhibited a contraction of the S-phase of the cell cycle compared with monolayer cultures, consistent with a non-replicating state, and enrichment of the stemness markers KLF4, Notch-1, Nanog and Sox2." (PMID 29651165, 2018). "Immunohistochemical (IHC) staining performed on 12 lung adenocarcinoma (LA) tissue samples showed protein expression of OCT4, NANOG, SOX2, KLF4 and c-MYC, and the CSC marker CD44." (PMID 34685477, 2021). "A mutual exclusive relationship between KLF4 and TERT expression levels was revealed in Lung Adenocarcinoma (TCGA, Nature 2014, 230 patients/230 samples)." (PMID 27153563, 2016). "The results showed that ADRB2 and KLF4 were significantly correlated with CD4+ T cells, CD8+ T cells, macrophages, NK cells, and neutrophils infiltration in lung adenocarcinoma (LUAD), notably both showing a positive correlation with the pro-tumoral macrophages." (PMID 40276761, 2025).
renal fibrosis (16 papers, 2015 to 2025). A final common manifestation of a wide variety of chronic kidney diseases characterized by glomerulosclerosis and tubulointerstitial fibrosis. "A decrease in KLF4 expression has been reported to be associated with the hypermethylation of the KLF4 promoter during EMT in renal fibrosis in vitro and in vivo." (PMID 34680284, 2021). "Future studies are required to elucidate the utility of methylated KLF4 as a diagnostic marker or therapeutic target in renal fibrosis." (PMID 25892014, 2015). "To the best of our knowledge, we demonstrate for the first time that the hypermethylation of KLF4 is associated with EMT in renal fibrosis and that this hypermethylation is regulated by Dnmt." (PMID 25892014, 2015). "KLF4 promoter methylation may thus be a promising diagnostic marker or therapeutic target in renal fibrosis." (PMID 25892014, 2015). "Moreover, it is implied that KLF4 may reduce inflammation stimulated by TGF-β1 in cases of renal fibrosis caused by diabetic nephropathy." (PMID 29747407, 2018). "Our data indicate that KLF4 up-regulates miR-101 expression, leading to the downregulation of COL10A1 expression, inhibition of EMT and renal fibrosis during the pathogenic process of I/R-related renal fibrosis." (PMID 38345033, 2024). "Decitabine, the most potent inhibitor of gene methylation, upregulated KLF4 in renal fibrosis by inhibiting the methylation of KLF4 promoter, which contributed to the inhibition of EMT." (PMID 37031197, 2023). "Overexpression of Klf4 also decreased HFD‐induced renal fibrosis, as indicated in Masson trichrome staining." (PMID 31800161, 2020). "In conclusion, our findings demonstrate that KLF4 is downregulated during EMT in renal fibrosis in vivo and in vitro; thus, KLF4 functions as a suppressor of renal fibrogenesis." (PMID 25892014, 2015). "In this review, we highlight recent findings on how KLF4 regulates renal fibrosis, with the aim of evaluating the potential of KLF4 as a novel therapeutic target for renal fibrosis." (PMID 26617530, 2015). "And a recent study has demonstrated that KLF-4 is downregulated during EMT in renal fibrosis and functions as a suppressor of renal fibrogenesis." (PMID 26839446, 2015). "In the present study, the expression, methylation status and function of KLF4 in renal fibrosis were investigated." (PMID 25892014, 2015). "Furthermore, since KLF4 is expressed in epithelial cells including tubular epithelium, the role of KLF4 in renal fibrosis is also featured." (PMID 29747407, 2018). "Together, these findings suggest that a change in the KLF4 level may be closely related to renal fibrosis." (PMID 26617530, 2015). "Therefore, KLF4 plays a catalytic role in renal fibrosis by inhibiting the differentiation and proliferation of VSMC." (PMID 26617530, 2015). "KLF4 is involved in renal fibrosis by regulating inflammation." (PMID 26617530, 2015). "Here, we summarize the recent progress made in understanding the role of KLF4 in renal fibrosis." (PMID 26617530, 2015). "Therefore, we tested whether KLF4 could modulate the miR-101/COL10A1 axis to affect renal fibrosis after AKI in mice and HK-2 cells." (PMID 38345033, 2024). "However, the expression and role of KLF4 in renal fibrosis remain undetermined." (PMID 25892014, 2015). "Together, these findings suggest that KLF4 may participate in the development of renal fibrosis, but that its inhibition of fibrosis is greater than its promotion of the condition, which suggests that KLF4 may serve as a novel therapeutic target for renal fibrosis." (PMID 26617530, 2015). "Collectively, these data suggest that KLF4-induced pre-miR-101 expression mitigates the hypoxia-enhanced Col10A1 expression, EMT, fibrosis, and tubular cell injury, contributing to renal fibrosis after AKI." (PMID 38345033, 2024).
renal fibrosis (continued). "Collectively, I/R-induced AKI promoted renal fibrosis in mice at 42 days post-induction by enhancing the EMT process in the kidney of mice and down-regulating the expression of KLF4 and miR-101 to enhance COL10A1 expression." (PMID 38345033, 2024). "Kruppel-like factor 4 (KLF4), a transcription factor, is crucial for renal fibrosis and kidney injury, and its expression is downregulated during kidney injury." (PMID 38345033, 2024). "These novel findings unveil that KLF4 modulates the miR-101/COL10A1 axis to inhibit EMT and renal fibrosis after AKI." (PMID 38345033, 2024). "However, the expression pattern and role of KLF4 during EMT in renal fibrosis remain unclear." (PMID 25892014, 2015). "The aim of the present study was to determine the epigenetic alterations of KLF4 and its potential role and mechanisms of action in epithelial-to-mesenchymal transition (EMT) in renal fibrosis." (PMID 25892014, 2015). "However, other studies have indicated that KLF4 may promote renal fibrosis." (PMID 26617530, 2015). "A complex relationship exists between KLF4 and TGF-β, which plays an important role in the development of renal fibrosis." (PMID 26617530, 2015). "DNMT1 could represses Krüppel-like factor 4(KLF4) through bind to its promoter regions and contributes to EMT in renal fibrosis." (PMID 29221147, 2017). "Moreover, the overexpression of KLF4 significantly reduced the production of MIF and MCP-1, which are important mediators of TGF-β-induced renal fibrosis." (PMID 26617530, 2015). "Nevertheless, the role of KLF4 in renal fibrosis is still not clear, there is a need for further study." (PMID 26617530, 2015). "Therefore high ANG II levels expected in CHF and the decreased RPO2 we observed in our studies could promote renal fibrosis in part by suppression of KLF15, KLF4, and E--Cadherin." (PMID 36091359, 2022).
breast ductal carcinoma (15 papers, 2010 to 2025). "For instance, high KLF4 expression has been shown for primary breast ductal carcinoma, being associated with cell migration and invasion." (PMID 41463190, 2025). "In human primary ductal carcinoma of the breast, KLF4 promotes tumor progression and the localization of KLF4 in the nucleus relates to poor prognosis." (PMID 37031197, 2023). "In the study of primary breast ductal carcinoma and oral squamous cell carcinoma, KLF4 expression was increased and cell proliferation was promoted." (PMID 33342082, 2021). "In primary breast ductal carcinoma, KLF4 maintains the stem cell-like features to enhance invasion and migration." (PMID 27835585, 2016). "The activation of Klf4 expression is found in immortalized kidney cells, laryngeal squamous cell carcinoma, ductal carcinoma of the breast and skin carcinoma." (PMID 26226504, 2015). "High KLF4 expression has been demonstrated in primary breast ductal carcinoma and oral squamous cell carcinoma." (PMID 22937066, 2012). "On the other hand, high Klf4 expression levels have been detected in primary ductal carcinomas of the breast and oral squamous cell carcinomas, and ectopic expression of Klf4 induced squamous epithelial dysplasia in mice." (PMID 20950440, 2010). "However, subsequent studies proposed the expression of Klf4 was upregulated in oral squamous carcinoma, primary breast ductal carcinoma and human skin squamous cell carcinoma, and correlated with carcinogenesis and tumor progression." (PMID 23599755, 2013). "Moreover, high KLF4 expression has been shown in primary breast ductal carcinoma and oral squamous cell carcinoma." (PMID 22937066, 2012). "Therefore, KLF4 may promote the progression of low malignancy primary ductal carcinoma of the breast, whereas KLF4 inhibits the progression of high malignancy triple-negative breast cancer." (PMID 37031197, 2023).
diabetes (15 papers, 2012 to 2025). "The high expression groups of PENK, EFEMP2, UBAP1, MAFF and KLF4 were mainly concentrated on diabetes mellitus (DM)." (PMID 38332532, 2024). "The present study aimed to investigate the roles of PIO and KLF4 in the transcriptional regulation of apelin in a high-fat diet/streptozotocin rat model of diabetes and in PIO-stimulated vascular smooth muscle cells (VSMCs)." (PMID 31829402, 2019). "In addition, KLF-4 and -7 relate to diabetes, while dysregulation of others further contributes to CVDs." (PMID 38672763, 2024). "However, in diabetes, the underlying epigenetic mechanism of KLF2 and KLF4 regulation in EC still remains elusive." (PMID 34685528, 2021). "Additionally, KLF4 has been thoroughly investigated in relation to diabetes and its consequences." (PMID 41196918, 2025). "Nonhealing wounds associated with diabetes are characterized by a prolonged inflammatory stage, and we found that IL-17A expression was significantly elevated in the ob/ob PU model but suppressed due to upregulation of KLF4." (PMID 34568499, 2021). "To determine whether this applies to our CMECs and whether the observed dysregulation of KLF expression in diabetes is linked to the observed MEF2D dysregulation in our diabetic models, we knocked down MEF2A or MEF2D in nondiabetic HCMECs and analyzed KLF2 and KLF4 gene expression." (PMID 36768805, 2023). "TF prediction analysis showed that NR3C1, TEAD and TFs that cooperate with YAP-TEAD, such as Klf4, SP1, AP1, MYC and ZEB1, were enriched in the DEGs of the diabetes vs. control comparison." (PMID 34970541, 2021). "Immunocytochemistry further validated robust expression of diverse pluripotency markers, including SSEA-4, TRA-1-60, TRA-1-81, OCT4, SOX2, KLF4 and NANOG in HK-derived iPS clones regardless of patient age and status of diabetes." (PMID 22308265, 2012).
neuroblastoma (15 papers, 2009 to 2025). Neuroblastoma (NB) is the most common solid, extracranial childhood tumor. "In a cohort of patients with neuroblastoma, a rare cancer of immature nerve cells, low expression of KLF4 was associated with poor clinical outcomes." (PMID 40552304, 2025). "In our study, many neuroblastoma cell lines with MYCN amplification exhibited increased expression of KLF4, indicating a potential contribution to the cell cycle dysregulation and the transformation process underlying neuroblastoma development." (PMID 37835497, 2023). "For example, it has been reported that KLF4 can promote cell differentiation, inhibition of cell cycles and also the activation of death pathways in neuroblastoma." (PMID 38794128, 2024). "N-Myc expression exhibits the inverse correlation with c-MYC in neuroblastomas and that the low transcriptional level of Klf4 is related with the poor clinical outcome of neuroblastoma patients." (PMID 30053872, 2018). "A combination of KLF4 plasmid and apigenin treatment increases apoptosis in the human malignant neuroblastoma SK-N-DZ and IMR-32 cell lines compared with control vector or single treatment." (PMID 29848383, 2018). "This binding was strongly attenuated in the N-myc minus cells, also supporting the notion that lif and klf4 are direct targets of N-Myc in neuroblastoma." (PMID 19495417, 2009). "LIN28 and KLF4 expression is also elevated by MYCN in neuroblastomas." (PMID 26023799, 2015). "Moreover, the overexpression of KLF4 in a neuroblastoma cell line suppressed cellular proliferation by upregulating p21, a cell cycle inhibitor, and shifted the phenotype of the cell to become more epithelial-like and non-tumorigenic, further highlighting KLF4’s link to cellular plasticity." (PMID 40552304, 2025). "Thus, N-Myc regulates expression of klf2, klf4, lif, and lin28b in human neuroblastoma." (PMID 19495417, 2009). "In human malignant neuroblastoma SK-N-DZ and IMR-32 cell lines, upregulation of KLF4 inhibited cell growth and increased cell apoptosis by activating caspase-3." (PMID 29848383, 2018). "Other validated mRNA targets of miR-10b include KLF4 in human oesophageal cancer cell lines and the nuclear receptor co-repressor 2 (NCOR2) in neuroblastomas." (PMID 23125021, 2012). "Klf4 overexpression in neuroblastoma cell SH-SY-5Y upregulated cell-cycle inhibitor protein p21(WAF1/CIP1), and knocking down p21 could partially rescue the suppressive effect of Klf4." (PMID 29212199, 2017). "klf4 and lin28b were strongly dependent on N-myc for their continued expression with reductions in the N-myc null NSC at a similar level to that observed in neuroblastoma, while klf2 was only weakly regulated." (PMID 19495417, 2009).
acute myeloid leukemia (14 papers, 2017 to 2026). Acute myeloid leukemia (AML) is a group of neoplasms arising from precursor cells committed to the myeloid cell-line differentiation. "KLF4 induces the expression of the NKG2D ligand MICA in acute myeloid leukemia cell lines; however, the function of KLF4-NKG2D in primary leukemic cells still requires additional investigation." (PMID 40589762, 2025). "Inhibits c-Myc expression, induces cell cycle arrest and apoptosis in acute myeloid leukemia cells; induces the Krüppel-like factor 4 (KLF4) tumor suppressor." (PMID 35337098, 2022). "To clarify the molecular basis of KLF4-mediated monocytic differentiation, we performed detailed genetic studies in acute myeloid leukemia (AML) cells." (PMID 33219287, 2020). "BAALC binder of MAP3K1 and KLF4 (BAALC) is a common oncogene in acute myelocytic leukemia (AML)." (PMID 32811810, 2020). "In terms of the p-value (padj), the most deregulated gene is BAALC (Brain And Acute Leukemia, Cytoplasmic), a gene responsible for acute myeloid leukemia (AML), and known to potentiate the oncogenic ERK pathway through interaction with MEKK1 and KLF4." (PMID 40700096, 2025). "In patients with acute myeloid leukemia (AML), ectopic expression of FOXC1 significantly inhibits KLF4 expression." (PMID 35504885, 2022). "Another study has also shown that miR-10a inhibited KLF4 and RB1-inducible coiled-coil 1(RB1CC1) regulated cell apoptosis in acute myeloid leukemia (AML)." (PMID 29848383, 2018).